MANF (mesencephalic astrocyte derived neurotrophic factor)
Diseases named in the same sentence as MANF in open-access papers (continued):
Sharing a sentence is not in itself a finding about the gene and the disease.
Wolfram syndrome (2 papers, 2020). Wolfram syndrome (WS) also known as DIDMOAD, is a neurodegenerative disorder characterized by type I diabetes mellitus (DM), diabetes insipidus (DI), sensorineural deafness (D), bilateral optical atrophy (OA) and neurological signs. "The proliferation of primary islets from βWfs1(−/−) mice, which is a mouse model of Wolfram syndrome, was also enhanced by MANF treatment." (PMID 32366942, 2020). "Here we show that MANF-based treatment prevents β cell death and enhances β cell proliferation in cell and mouse models of Wolfram syndrome." (PMID 32366942, 2020). "Collectively, these results indicate that MANF enhances β cell survival and proliferation in cell and mouse models of Wolfram syndrome." (PMID 32366942, 2020). "In this study, we show that MANF treatment activates the proliferation of β cells in human islets and prevents ER stress-mediated β cell death and enhances β cell proliferation in cell and mouse models of Wolfram syndrome." (PMID 32366942, 2020). "Furthermore, we have recently reported that MANF prevents ER stress-mediated β-cell death in cell and mouse models of Wolfram syndrome." (PMID 33299977, 2020). "Here, we show that mesencephalic astrocyte-derived neurotrophic factor (MANF), a neurotrophic factor secreted from ER stressed cells, prevents ER stress-mediated β cell death and enhances β cell proliferation in cell and mouse models of Wolfram syndrome, a prototype of ER disorders." (PMID 32366942, 2020). "It has been demonstrated that MANF plays a critical role in the survival of ER stressed β cells and neurons, raising the possibility that MANF-based treatment can be beneficial for patients suffering from ER stress-related disorders, including Wolfram syndrome." (PMID 32366942, 2020).
abortion (1 paper, 2024). the ending of pregnancy by removing a fetus or embryo before it can survive outside the uterus.
alcohol use disorder (1 paper, 2021). "Unlike GDNF and BDNF, the role of MANF and CDNF in addiction and, particularly, in alcohol use disorder has not be studied extensively." (PMID 34923968, 2021). "However, the role of MANF and CDNF in addiction and, particularly, in alcohol use disorder is not clear." (PMID 34923968, 2021).
alcoholic pancreatitis (1 paper, 2023). Acute or chronic inflammation of the pancreas due to excessive alcohol drinking. "Further studies using human samples and experimental models are necessary to elucidate MANF’s role in alcoholic pancreatitis." (PMID 36830970, 2023). "It is also possible that the lower acinar MANF levels exacerbate alcoholic pancreatitis, which is consistent with our previous findings in a cell culture model." (PMID 36830970, 2023).
Azoospermia (1 paper, 2024). Absence of any measurable level of sperm,whereby spermatozoa cannot be observed even after centrifugation of the semen pellet. "This preliminary investigation involved measuring and comparing the serum protein levels of PDIA1, PDIA3, MANF, GRP78, CLU, CRT, and CNX in patients diagnosed with idiopathic nonobstructive azoospermia and noninfertile male controls." (PMID 39237030, 2024).
cardiac hypertrophy (1 paper, 2025). "Under the pathological state of cardiac hypertrophy, the binding of MANF to BAX can decrease BAX mitochondrial membrane translocation and cytochrome c release to cytoplasm, eventually relieving caspase‐dependent cardiomyocyte apoptosis." (PMID 40739335, 2025).
cervical cancer (1 paper, 2024). A primary or metastatic malignant neoplasm involving the cervix. "This study also found that silencing of endogenous MANF expression with siRNA in HeLa cells—a cervical cancer cell line—increased cell proliferation ability, despite making the cells more susceptible to endoplasmic reticulum stress-induced death." (PMID 38164189, 2024).
chondrodysplasia (1 paper, 2019). "However, the role of MANF in cartilage and in the pathobiology of chondrodysplasias remains largely unknown." (PMID 30543055, 2019).
dyslipidemia (1 paper, 2022). "Thus, the effect of antidepressants in improving dyslipidemia may be mediated by the MANF/EWSR1/ANXA6 pathway, which is worthy to be investigated in the future." (PMID 36585419, 2022).
Hearing impairment (1 paper, 2022). A decreased magnitude of the sensory perception of sound. "There is a future need for identification of MANF mutations in large clinical databases to understand the progression and severity of this hearing impairment." (PMID 34815294, 2022).
hearing loss (1 paper, 2022). "In summary, we show that MANF promotes the structural and functional maintenance of auditory hair cells in mice predisposed to genetic age-related hearing loss." (PMID 34815294, 2022). "This could be the case in the cochlear hair cells as well, and the down-regulation of MANF or components of the UPR could have an exacerbating effect on age-related progressive hearing loss." (PMID 34815294, 2022).
hematoma (1 paper, 2023). A hematoma is a collection of blood from a vascular structure into an extravascular space. "Alternatively, two combination models shown as nomograms, which contained serum MANF levels, NIHSS scores and hematoma volumes, were built to discriminate risk of END and a poor prognosis." (PMID 37268902, 2023). "END and prognostic predictive abilities were similar between serum MANF levels and NIHSS scores plus hematoma volumes (all P > 0.05)." (PMID 37268902, 2023). "Combination of serum MANF levels with NIHSS scores and hematoma volumes had significantly higher prognostic capability than each of them (both P < 0.05)." (PMID 37268902, 2023). "Intriguingly, serum MANF levels combined with NIHSS scores and hematoma volume showed insignificantly higher END predictive capability than NIHSS scores and hematoma volume alone (both P > 0.05)." (PMID 37268902, 2023). "Interestingly, prognostic predictive ability of combination of serum MANF levels with NIHSS scores and hematoma volume was substantially superior to that of NIHSS scores and hematoma volume alone (both P < 0.05)." (PMID 37268902, 2023).
hemorrhage (1 paper, 2022). Loss of blood from the vascular compartment to the exterior or into nonvascular body space as a result of rupture or severance of the blood vessels. "In both intracerebral hemorrhage and subarachnoid hemorrhage rat models, MANF protein expression increased 3 h after hemorrhage, peaked at 24 h, and remained elevated up to 72 h post-hemorrhage in the peri-hematoma area." (PMID 35783104, 2022).
hemorrhagic stroke (1 paper, 2022). A stroke caused by a bleed on the brain. "Furthermore, hemorrhagic stroke has been shown to increase MANF protein expression, mainly in neurons." (PMID 35783104, 2022).
hyperlipidemia (1 paper, 2024). "A study concluded that low-density lipoprotein cholesterol (LDL-C) was found to be higher in MDD patients than HCs, and another study found higher serum MANF levels in patients with hyperlipidemia along with high levels of LDL-C." (PMID 38216957, 2024).
hyperplasia (1 paper, 2021). An abnormal increase in the number of cells in an organ or a tissue with consequent enlargement. "Hyperplasia was only correlated to MANF and EML4 according to the MS/MS analysis." (PMID 35008858, 2021).
hypopituitarism (1 paper, 2019). A condition of diminution or cessation of secretion of one or more hormones from the anterior pituitary gland. "As growth retardation in human is associated with hypopituitarism and growth hormone-deficiency, we set out to study the effect of MANF-removal from the pituitary gland in mice." (PMID 31781038, 2019).
infertile (1 paper, 2024). "The Cohen's d values for markers such as PDIA3, MANF, and GRP78 were 1.633, 0.574, and 0.766, respectively, strongly supporting the association of these proteins with infertility." (PMID 39237030, 2024). "Our findings demonstrate elevated MANF serum levels in infertile individuals, representing the first report of such data." (PMID 39237030, 2024). "Based on this review, we selected PDIA1, PDIA3, MANF, GRP78, CLU, CRT, and CNX as chaperones for validation as serum-based biomarkers in potentially infertile populations." (PMID 39237030, 2024). "Specifically, we found that the levels of PDIA3, MANF, and CRT were increased in the infertile male group compared to the control group." (PMID 39237030, 2024). "Serum PDIA1 (P = 0.0004), MANF (P = 0.018), PDIA3 (P < 0.0001), GRP78 (P = 0.0027), and CRT (P = 0.0009) levels were higher in the infertile group compared to the control." (PMID 39237030, 2024). "In the analysis of the results from various GEO databases, it was observed that the mRNA expression levels of the human targets PDIA3, MANF, CLU, CRT, and CNX were decreased in the infertile male group compared to the control group, as reported in the respective data sets." (PMID 39237030, 2024).
intracerebral hemorrhage (1 paper, 2023). A cerebrovascular disorder characterized by bleeding into one or both cerebral hemispheres including the basal ganglia and the cerebral cortex. "We intended to determine significance of serum MANF as a prognostic biomarker of intracerebral hemorrhage (ICH)." (PMID 37268902, 2023).
kidney damage (1 paper, 2024). "Likewise, the expression of genes such as MANF, which is a cytoprotective gene with anti-inflammatory and anti-oxidative properties in kidney damage, is not modulated by JQ1 61-64." (PMID 38481808, 2024).
leukemia (1 paper, 2021). A malignant (clonal) hematologic disorder, involving hematopoietic stem cells and characterized by the presence of primitive or atypical myeloid or lymphoid cells in the bone marrow and the blood. "In a study aiming to map the interaction network of an ER-localized chaperone GRP94 in the mouse preB leukemia cells, MANF was found to be one of the interacting proteins." (PMID 33460650, 2021).
macular holes (1 paper, 2017). A hole in the macula of the retina. "As we expected, MANF was found in the human vitreous, and MANF levels were elevated under pathological conditions, such as proliferative diabetic retinopathy and retinal detachment, compared with macular holes." (PMID 28367115, 2017). "Furthermore, patients with proliferative diabetic retinopathy and retinal detachments showed a significantly higher MANF level compared with patients with macular holes." (PMID 28367115, 2017). "The mean levels of MANF in the vitreous samples from patients with proliferative diabetic retinopathy (n = 21) (3.44 ± 1.07 ng/ml) and retinal detachments (n = 16) (3.43 ± 1.09 ng/ml) were significantly higher than those in patients with macular holes (n = 18) (1.21 ± 0.28 ng/ml) (p < 0.001)." (PMID 28367115, 2017). "With the use of ELISA assay kits, we detected MANF in all vitreous fluid samples from different retinopathies, including proliferative diabetic retinopathy (with or without vitreous hemorrhage), macular holes, and retinal detachment." (PMID 28367115, 2017).
male infertility (1 paper, 2024). The inability of the male to effect fertilization of an ovum after a specified period of unprotected intercourse. "In this context, PDIA3, MANF, PDIA3, GRP78, and CRT emerge as particularly promising candidates for further investigation and potential clinical application in the diagnosis of male infertility." (PMID 39237030, 2024). "The areas under the curve and P-values calculated from the ROC curve analysis suggest that PDIA3, MANF, GRP78, and CRT could serve as potential biomarkers for diagnosing male infertility." (PMID 39237030, 2024).
membranous nephropathy (1 paper, 2022). "Rats with podocyte diseases (experimental membranous nephropathy and FSGS) showed increases in various glomerular ER chaperones and increased urinary non-KDEL chaperones, including ERdj3 (DNAJB11) and mesencephalic astrocyte-derived neurotrophic factor (MANF), coinciding with proteinuria." (PMID 39086958, 2022).
memory impairment (1 paper, 2020). "Thus, despite increased expression of Grp78 and sXbp1 mRNA in the hippocampus of Manffl/fl::NestinCre/+ mice, behavioral tests showed that MANF deficiency does not result in memory impairment." (PMID 32005751, 2020).
metastatic cancers (1 paper, 2024). A carcinoma which has spread from the original site of growth to another anatomic site. "Prior research has also indicated that GRP170 could be employed for the development of specific chaperone vaccines to address metastatic cancers, while MANF could be a promising therapeutic biomarker for ERS-related diseases." (PMID 39114033, 2024).
Miscarriage (1 paper, 2024). A pregnancy that ends at a stage in which the fetus is incapable of surviving on its own, defined as the spontaneous loss of a fetus before the 22th week of pregnancy. "Conversely, MANF downregulation in mice was shown to reverse these effects on the occurrence of miscarriage in animal experiments." (PMID 38164189, 2024). "We observed that MANF co-localized and interacted with NPM1 in the nucleus of trophoblast cells from URM samples, interfering with NPM1 expression, a mechanism that may be involved in the process of miscarriage." (PMID 38164189, 2024). "To determine whether MANF expression levels correlated with gestational status or miscarriage, we also tested 20 healthy non-pregnant women and followed up on 19 women in the URM group 6 months after they underwent an artificial abortion." (PMID 38164189, 2024). "Here, we found that MANF levels in the peripheral blood and aborted tissue of URM women were higher than in normal controls, irrespective of pregnancy or miscarriage." (PMID 38164189, 2024).
nephrolithiasis (1 paper, 2024). The presence of a calculus in the pelvis of the kidney; this is most often composed of mineral salts and proteins. "Overall, studying HYOU1, HSPA5, and MANF could provide deeper insight into the role of ER stress in the pathogenesis of urolithiasis and their potential as novel targeted therapeutic approaches for nephrolithiasis." (PMID 39114033, 2024).
nephrotic syndrome (1 paper, 2023). A collection of symptoms that include severe edema, proteinuria, and hypoalbuminemia; it is indicative of renal dysfunction. "In kidney disease, MANF’s role in ER stress-related cell signaling gains prominence, particularly in nephrotic syndrome and glomerular/tubular disorders." (PMID 37751132, 2023).
Neurodevelopmental delay (1 paper, 2022). "Recently, childhood-onset diabetes and a neurodevelopmental delay caused by the MANF gene variant have been reported." (PMID 36613674, 2022).
osteoarthritis (1 paper, 2021). A noninflammatory degenerative joint disease occurring chiefly in older persons, characterized by degeneration of the articular cartilage, hypertrophy of bone at the margins and changes in the synovial membrane. "This study provides the first evidence that MRL MSC induce ear hole regeneration and protect mice from osteoarthritis through their high capacity to release MANF." (PMID 33738280, 2021).
pancreatitis (1 paper, 2023). Inflammation of the pancreas. "As both alcohol and ER stress response proteins are involved in the pathogenesis of pancreatitis, we sought to investigate the expression of MANF in chronic alcoholic pancreatitis (CAP) and chronic non-alcoholic pancreatitis (CNP)." (PMID 36830970, 2023).
papillary carcinoma (1 paper, 2025). A malignant epithelial neoplasm characterized by a papillary growth pattern. "Moreover, after normalized by VHL expression, MANF expression correlated with the OS and DFS of ccRCC patients, which was not seen in papillary carcinoma and chromophobe." (PMID 40603319, 2025).
prion disease (1 paper, 2025). A transmissible disease that is caused by a protein that is able to induce abnormal folding of normal cellular proteins, leading to characteristic spongiform brain changes, which are associated with neuronal loss without an inflammatory response. "We also found that reduced protein expression of a further gene product previously unconnected to prion diseases, MANF, was associated with increased sCJD risk in the PWAS." (PMID 39865733, 2025).
proliferative diabetic retinopathy (1 paper, 2017). Advanced retinopathy due to diabetes mellitus characterized by the formation of new vessels in the retina. "The MANF levels were clearly lower in the vitreous samples from patients with pure proliferative diabetic retinopathy (n = 8) (2.07 ± 0.14 ng/ml) compared with those from the patients with proliferative diabetic retinopathy with vitreous hemorrhage (n = 13) (3.77 ± 0.97 ng/ml) (p < 0.01)." (PMID 28367115, 2017).
proteinopathy (1 paper, 2023). "Together, we have discovered MANF as a biotherapeutic protein and elucidated previously unknown mechanisms of MANF in the regulation of organelle homeostasis, which may have broad therapeutic applications to treat various proteinopathies." (PMID 37838725, 2023). "Taken together, our findings reveal the role of MANF in maintaining functional autophagy, and highlight the important therapeutic function of MANF by regulating organelle homeostasis for the treatment of ADTKD and possibly other toxic proteinopathy." (PMID 37838725, 2023).
pterygium (1 paper, 2012). A wedge-shaped fibrovascular lesion arising from the bulbar conjunctiva and extending to the cornea. "Several growth factors such as VEGF and MANF and interleukins such as IL-6 were elevated in pterygium cells exposed to doxycycline." (PMID 22724003, 2012).
renal carcinoma (1 paper, 2022). A carcinoma arising from the epithelium of the renal parenchyma or the renal pelvis. "MANF, also named arginine-rich mutated in early tumors (ARMET) or arginine-rich protein (ARP), is found to be mutated in different human solid tumors, including lung, breast, prostate, pancreatic, and renal cancer in the 1990s." (PMID 36185184, 2022).
renal fibrosis (1 paper, 2023). A final common manifestation of a wide variety of chronic kidney diseases characterized by glomerulosclerosis and tubulointerstitial fibrosis. "Light microscopic examination of Picrosirius red-stained kidney sections revealed less renal fibrosis at 24 weeks in the UmodC147W/+; MANF/P8TA kidneys vs. UmodC147W/+;P8TA kidneys at 24 weeks." (PMID 37838725, 2023). "MANF deletion in mutant TALs exacerbates autophagy failure and renal fibrosis." (PMID 37838725, 2023).
status epilepticus (1 paper, 2018). Status epilepticus is defined as a continuous seizure lasting more than 30 min, or two or more seizures without full recovery of consciousness between any of them. "In vivo, transient upregulation of MANF mRNA was found in the adult rat brain after status epilepticus and global forebrain ischemia." (PMID 29966219, 2018).
subarachnoid hemorrhage (1 paper, 2022). A serious neurological disorder characterized by intracranial hemorrhage into the subarachnoid space. "Comparable results were found in a rat model of subarachnoid hemorrhage, and an additional finding of MMP-9 downregulation suggested MANF may protect the integrity of the BBB." (PMID 35783104, 2022).
ulcerative colitis (1 paper, 2025). An inflammatory bowel disease involving the mucosal surface of the large intestine and rectum. "It was also demonstrated that intravenous administration of recombinant human His-MANF protein significantly alleviated acute ulcerative colitis in mice by regulating the activation of congenital immune inflammatory response." (PMID 40115964, 2025). "Previous studies have indicated that intravenous administration of 1 mg/kg/day recombinant human MANF protein with His tag (His-MANF) for 3 days can ameliorate acute ulcerative colitis in mice." (PMID 40115964, 2025).